ITCH (itchy E3 ubiquitin protein ligase)
Diseases named in the same sentence as ITCH in open-access papers (continued):
Sharing a sentence is not in itself a finding about the gene and the disease.
tumor (94 papers, 2014 to 2026). "Downregulated circ-ITCH was significantly associated with high pathological tumor stage in BCa patients." (PMID 35296022, 2022). "Recent studies have found that circ-ITCH is closely linked to clinicopathological characteristics and can be employed as a tumor prognostic biomarker, which will aid in tumor treatment." (PMID 35910224, 2022). "In summary, our meta-analysis revealed that low circ-ITCH expression was significantly associated with larger tumor sizes, advanced TNM stage, increased LNM, and poor survival rate in cancers." (PMID 33623789, 2021). "We found that low circ-ITCH expression was significantly associated with Tumor size (p = 0.0009) and FIGO stage (p = 0.0021)." (PMID 32714095, 2020). "In ESCC, circ_0067934 is significantly upregulated and associated with poor differentiation, whereas cir-ITCH is downregulated and functions as a tumor inhibitor by regulating tumor cell viability." (PMID 30126353, 2018). "Taken together, these findings implicated a remarkably tumor-suppressor role of circ-ITCH in most cancers." (PMID 29386015, 2018). "Cir-ITCH competitively bound to tumor-associated miRNAs (miR-7, miR-17, and miR-214) to up-regulate the expression of ITCH, promoting the ubiquitination and degradation of phosphorylated Dvl2, and thereby inhibiting the activation of Wnt/β-catenin pathway." (PMID 29096676, 2017). "The target genes of ITCH (including p63, p73, Dvl2, and Notch1) are closely associated with tumor formation and chemotherapy sensitivity." (PMID 29096676, 2017). "These proteins usually associated with tumor formation and chemosensitivity serve as either tumor suppressor or enhancer; thus, the role of ITCH in tumor progression is complicated." (PMID 27642589, 2016). "ITCH’s targets, including p63, p73, and Notch1, are usually associated with tumor formation and chemosensitivity, demonstrating the connection of ITCH to cancer biology." (PMID 26110611, 2015). "Although circular RNA ITCH (CircITCH) is a broad-spectrum tumor-suppressive circular RNA, its encoding gene ITCH (E3 ubiquitin ligase) has been found to reduce renal cell apoptosis, alleviate oxidative stress markers, and decrease levels of inflammatory factors." (PMID 40989844, 2025). "By analysing the association between circ-ITCH expression and BC clinical criteria, low circ-ITCH expression was more significantly prone to lymph node metastasis (p = 0.003), larger tumour size (p = 0.04), advanced TNM stage (p = 0.004), and histological grade (p = 0.003)." (PMID 37370928, 2023). "In addition, we discovered that low circ-ITCH expression was more strongly associated with lymph node metastasis, larger tumour size, advancing TNM stage, and histological grade." (PMID 37370928, 2023). "Furthermore, the expression of circ-ITCH has been linked to tumor size, tumor grade, TNM stage and clinical stage." (PMID 35910224, 2022). "In all three cancer types, cir-ITCH activity could increase the level of ITCH protein, a regulator of several tumor-associated proteins, which is involved in the inhibition of the Wnt/β-catenin signaling pathway." (PMID 29349062, 2017). "However, ITCH expression was significantly associated with tumor cell differentiation (P = 0.018) and distant metastasis (P = 0.001)." (PMID 26621835, 2016). "Latterly, ITCH was found to be crucial in the control of proteasome degradation of several important substrates such as p63, p73, Notch1, and Dvl2; all of which are usually associated with tumor formation and chemosensitivity." (PMID 25749389, 2015). "In contrast, increased expression of ITCH resulted in decreased signaling activity of the Wnt/β-catenin, reduced cell proliferation and tumor growth." (PMID 40136647, 2025). "In an effort to bring more efficacious treatments to patients, we targeted the down regulation of ITCH, an E3 ligase that is overexpressed in a variety of cancers, and which inhibits P73, a tumour suppressor gene." (PMID 38931949, 2024).
tumor (continued). "RASSF1A gets recruited to the TGF-β receptor I and degraded via the ITCH E3 ligase, effectively eliminating its tumor-suppressive activity and potentially promoting tumor invasion." (PMID 38926528, 2024). "Circ-ITCH overexpression acts as a tumor suppressor and prevents PTC progression by sequestering miR-22-3p." (PMID 39524849, 2024). "Circ-ITCH controls malignant tumour growth, invasion, migration, and apoptosis, suggesting its role as a key tumour suppressor." (PMID 37370928, 2023). "A mounting body of reports exhibits the multifaceted oncogenic and tumor suppressor functions of ITCH in different human malignancies, due to its dynamic and context-dependent role in tumor cells." (PMID 36918822, 2023). "These outcomes suggest that circ-ITCH is a tumour suppressor gene and is essential for BC progression." (PMID 37370928, 2023). "While circ-ITCH is low expressed in a number of malignancies, it is unclear which tumor has greater specificity and accuracy about circ-ITCH, meriting additional investigation." (PMID 35910224, 2022). "According to relevant studies, circ-ITCH mainly acts as a tumor suppressor in diverse cancer cell lines." (PMID 35327551, 2022). "In oral squamous cell carcinoma (OSCC), circ-ITCH serves as a tumor suppressor by functioning as miR-421 sponge, subsequently increasing expression on PDCD4." (PMID 35327551, 2022). "Overall, in almost all cancers, circ-ITCH, which is known as a tumor suppressant, inhibits cell proliferation and cancer growth rate." (PMID 35327551, 2022). "Circ-ITCH is a promising therapeutic target since it has an anti-tumor impact that is connected to a range of substances and pathways, as evidenced by recent studies." (PMID 35910224, 2022). "We suggest that JAK2 increases GMP expansion through its inhibitory effect on NOTCH via the MAPK pathway and ITCH and so predict a tumour suppressor role for NOTCH in the GMP cell population." (PMID 36192425, 2022). "The ITCH gene is present in rat brains, but, crucially, is present in human tumours and presents a potential context-dependent therapeutic target." (PMID 36140283, 2022). "On the contrary, circ-ITCH originates from few exons of ITCH, a ubiquitin-ligase E3, which plays a tumor suppressor by facilitating ubiquitin degradation of DVL2 (Dishevelled segment polarity protein 2) to repress typical Wnt signaling pathway." (PMID 35697671, 2022). "Ren et al105 also found that circ‐ITCH played asa tumour suppressor in progression of osteosarcoma by modulating miR‐22." (PMID 33103338, 2021). "Future studies should examine the crosstalk between ITCH and immunity and design specific ITCH inhibitors to better understand and target ITCH signal molecules in human cancer and improve the effect of tumor immunotherapy." (PMID 34943817, 2021). "For example, circ-ITCH acts as a tumor suppressor in multiple tumors, and inhibits progression of multiple tumor types by sponging different miRNAs (miR-17, miR-224, miR-22 and miR-214) and regulating the target genes of miRNAs." (PMID 34055634, 2021). "It is worth exploring the relationship between circ-ITCH expression and tumor metastasis levels in ccRCC patients." (PMID 33969128, 2021). "Accumulating evidence has implied that circ-ITCH exert tumor-suppressor function in these cancers by acting as a sponge for oncogenic microRNAs." (PMID 33623789, 2021). "circ-ITCH overexpression inhibited PCa cell proliferation and increased apoptosis in vitro, also repressed tumor growth in vivo." (PMID 34804984, 2021). "The downregulation of ITCH greatly influences the antigen recognition and activation of the adaptive immune system, thus leading to the inhibition of tumor immune response." (PMID 34912899, 2021). "Low circ-ITCH expression correlated with advanced clinicopathological characteristics including higher tumor stage, Gleason score and high PSA levels." (PMID 34804984, 2021).
tumor (continued). "Together, the findings indicate that ITCH inhibitors play a vital role in tumor immunotherapy, providing valuable information for the development of new immunotherapy methods with potential clinical applications." (PMID 34943817, 2021). "Major histocompatibility complex (MHC) class I-mediated tumor antigen processing was the hub pathway that was significantly downregulated in lgCMN, and ITCH, FBXW7, HECW2, and WWP1 were identified as candidate hub genes." (PMID 34912899, 2021). "On one hand, studies have shown ITCH acting as a tumor suppressor by regulating HER2 and FLIP in breast and brain cancers, respectively." (PMID 34322378, 2021). "Functionally, accumulating evidence has implied a tumor-suppressor role circ-ITCH in diverse cancers." (PMID 33623789, 2021). "Circ-ITCH can act as a sponge of miR-7 and miR-20a to inhibit the negative regulatory effect of the latter on the target gene ITCH, while ITCH has a tumor suppressor function by inhibition of the Wnt/β-catenin signaling pathway." (PMID 32884449, 2020). "Taken together, these data demonstrated that cir-ITCH plays a tumor-suppressive role in human PCa cells, partly through the Wnt/β-catenin and PI3K/AKT/mTOR pathways." (PMID 32904490, 2020). "Collectively, ITCH participates in numerous pathways, and loss of its expression causes craniofacial abnormalities hepatomegaly and severe inflammation in human; while an increased level of ITCH might otherwise enhance tumorigenesis or enhance the anti‐tumor role of WWOX." (PMID 32259050, 2020). "The circRNA-ITCH and hsa_circ_0043256 functioned as tumor suppressors in LC by up-regulating ITCH expression and inhibiting the activation of Wnt/β-catenin pathway; the expression of cir-ITCH was found to be decreased in LC43." (PMID 32071550, 2020). "Another circRNA with remarkable function is circ-ITCH, which acts as a tumor-suppressor via increasing the expression of its linear ITCH transcripts by its miRNA-sponging activity." (PMID 32878117, 2020). "The molecule we chose to target is ITCH, the E3 ubiquitin ligase responsible for the degradation of a panel of tumour suppressor genes, including TP73." (PMID 31974512, 2020). "Results suggested that tumor volume and weight were significantly reduced in circ-ITCH overexpression group." (PMID 32714095, 2020). "ITCH negatively regulates the Hippo tumor suppressor pathway by building a K48-linked polyubiquitin chain on of the serine/threonine kinase LATS1, a tumor growth inhibitor that induces G2-M arrest and apoptosis." (PMID 30229450, 2019). "Specifically, ITCH silencing or CI blocked 9F7-F11-induced caspase-8-mediated apoptosis of tumor cells, and restored c-FLIP expression." (PMID 31443721, 2019). "They stated that circ-ITCH acts as a tumour suppressor by a circ-ITCH/miR-17, miR-224/p 21, PTEN axis in bladder cancer." (PMID 31875034, 2019). "9F7-F11 sensitized tumor cells to caspase-mediated apoptosis through ITCH-dependent c-FLIP downregulation." (PMID 31443721, 2019). "To demonstrate the effects of ITCH knockdown in vivo, we used tumor xenograft mouse models of MDA-MB-231 cells." (PMID 30517763, 2019). "Here, we report that ITCH-dependent proteasomal degradation of c-FLIP induced by the anti-HER3 antibody 9F7-F11 favors DR5/caspase 8-mediated apoptosis of tumor cells." (PMID 31443721, 2019). "We found that 9F7-F11 sensitizes tumor cells to DR5/caspase-8-mediated apoptosis through ITCH-dependent downregulation of c-FLIP." (PMID 31443721, 2019). "Circ-ITCH is a circRNA generated from several exons of itchy E3 ubiquitin protein ligase (ITCH) and tumor suppressor served as a sponge for certain miRNAs targeting their parental transcripts of ITCH." (PMID 29386015, 2018). "Compared with the GFP group, circ-ITCH overexpression group significantly reduced the mean tumor volume (P < 0.05) and average tumor weight (P < 0.01) than those of GFP group." (PMID 29386015, 2018).
tumor (continued). "Specifically, we observed a dramatic decrease of circ-ITCH expression not only in BCa tissues but also in BCa cell lines, suggesting its tumor-suppressive effect." (PMID 29386015, 2018). "In lung cancer and colorectal cancer, downregulated circ-ITCH plays an important tumor suppressor role." (PMID 30126353, 2018). "LITAF is a tumor suppressor that was previously reported to physically interact with ITCH and induce the relocation of ITCH to the lysosomes, likely interfering with ITCH function." (PMID 30285739, 2018). "It has shown that the role of cir-ITCH in tumor formation and chemosensitivity through miRNA regulation is mediated by Wnt/β-catenin signaling pathway via ubiquitination and degradation of phosphorylated Dvl2." (PMID 28969093, 2017). "ITCH is an important molecule in the Wnt/β-catenin pathway, which regulates protein stability, immune responses, and tumor development." (PMID 29096676, 2017). "As we know, ITCH is an anti-cancer protein targeting p63, p73, and Notch1 gene and usually involve in tumor formation and chemosensitivity." (PMID 28279183, 2017). "The results show that there is low expression of cir-ITCH in ESCC tumor tissues, and that cir-ITCH reduces cell viability, and arrests proliferation in ESCC cells." (PMID 25749389, 2015). "Intriguingly when co-expressed together, ITCH and AMOT/p130 were shown to suppress cell growth, confirming an anti-tumor effect of ITCH." (PMID 25350971, 2014). "ITCH is involved in the control of inflammatory signaling pathways and also has a multifaceted role in human cancers, acting in context-dependent fashion as either an oncogene or tumor suppressor." (PMID 37957138, 2023). "Furthermore, there is a correlation between the expression of circ-ITCH and tumour size, tumour grade, TNM stage, and clinical stage." (PMID 37370928, 2023). "While other of them are lowly expressed in tumor tissues, which can continuously activate their host genes and inhibit the malignant phenotype of tumors as tumor suppressors, such as circ-Foxo3, circ-ITCH and circ-FBXW7." (PMID 37060016, 2023). "Cir-ITCH, generated from ITCH, could enhance the expression of ITCH via sponging miRNAs such as miR-7, miR-17 and miR-214, thereby increasing c-Myc expression to induce cell proliferation and tumor growth." (PMID 35672804, 2022). "In short, recent studies have discovered that circ-ITCH regulates the expression level of a number of cell cycle-related proteins, as a ceRNA, to induce tumor cell apoptosis and limit tumor cell growth, thereby acting as an anti-tumor agent." (PMID 35910224, 2022). "According to recent research, circ-ITCH also has an important role in non-tumor tissue." (PMID 35910224, 2022). "The pooled ORs with their 95% CIs showed that low circ-ITCH expression was significantly associated with larger tumor size, increased LNM, and advanced TNM stage, indicating that low circ-ITCH expression was an indicator of aggressive clinicopathological parameters." (PMID 33623789, 2021). "To verify the role of circ-ITCH in vivo, we established a xenograft tumor mouse model of ccRCC." (PMID 33969128, 2021). "On the other hand, evidence has suggested that ITCH might also function as a tumor promoter by downregulating Smad7, prompting TGF-β to promote Epithelial Mesenchymal Transition (EMT) in breast cancer cells." (PMID 34322378, 2021). "A xenograft tumor model was established to evaluate the role of circ-ITCH in vivo." (PMID 33969128, 2021). "In vivo experimental results also proved that β-catenin expression in xenograft tumours could be suppressed by cir-ITCH, while miR-17 could restore β-catenin expression." (PMID 33060778, 2020). "Then, we assessed ITCH expression in tumour xenografts through immunohistochemical analysis." (PMID 33060778, 2020).
tumor (continued). "Our data suggest that ITCH could be silenced both in vitro and in vivo using nanoparticles, and silencing of ITCH sensitizes the tumour cells to irradiation treatment." (PMID 31974512, 2020). "The functional role of circ-ITCH was measured by xenograft tumor model in vivo." (PMID 32714095, 2020). "In this study, we tested the hypothesis that modulation of ITCH expression would enhance the sensitivity of the tumour cells to treatment." (PMID 31974512, 2020). "Furthermore, RT-qPCR and western blot analysis indicated that the expression levels of circ-ITCH and CDH1 were increased, whereas the miR-106a level was decreased in tumor tissues in circ-ITCH-overexpression group." (PMID 32714095, 2020). "Thus, we provide evidence that the ITCH-mediated K46 H1.2 cascade is required for tumor growth and metastatic progression." (PMID 30517763, 2019). "Meanwhile in vivo experiments also supported the tumor-suppressive function of circ-ITCH in BCa." (PMID 29386015, 2018). "More important, whether there exists other regulatory axis for circ-ITCH regulating tumor progression, besides the classic pathway above, was still unknown." (PMID 29386015, 2018). "ITCH E3 ligase was also connected to tumor invasion and metastasis." (PMID 30619734, 2018). "Does it antagonize ITCH function and suppresses tumor growth?" (PMID 30619734, 2018). "Therefore, circ-ITCH protected ITCH and blocked the downstream Wnt/β-catenin signaling, which resulted in arresting tumor progression." (PMID 29386015, 2018). "Based on our in vitro findings, we hypothesized that inhibiting ITCH expression might impact tumor cell colonization and metastasis." (PMID 26621835, 2016). "To complement our in vitro findings demonstrating that ITCH induces tumor initiation and progression by activating YAP with an in vivo model, we injected GFP-labeled MCF10A-RAS/ITCH and MCF10A-RAS/ITCH/YAP-sh cells into MFP of Nod-SCID mice and followed tumor development and progression." (PMID 25350971, 2014). "In addition, Circ-ITCH is a tumor suppressor in many cancers." (PMID 35513849, 2022). "Recently, studies have revealed that circ-ITCH is down-regulated in multiple tumor tissues, and regulates cell proliferation, migration, invasion and apoptosis of malignant tumor, indicating it might be an important tumor suppressor." (PMID 35910224, 2022). "This suggests that ITCH may exert tumour-suppressive functions." (PMID 34831354, 2021). "Furthermore, cir-ITCH expression was correlated with tumour metastasis." (PMID 33060778, 2020). "circRNA-ITCH may serve as a tumor suppressor by upregulating ITCH expression." (PMID 31324812, 2019). "Here, we verified that Jun B plays a tumour suppressive role in the tumorigenesis of LUSC, and the regulation of itself occurs through its protein degradation modulated by its E3 ligase ITCH‐mediated its protein degradation." (PMID 39099000, 2024). "In addition, ITCH‐mediated ubiquitination can perform a tumor‐suppressive role via impaired degradation of WWOX, which may be due to the fact that most of the evidence accumulated to date on the role of ITCH in tumorigenesis has come from in vitro or in vitro models." (PMID 38342606, 2024). "All in all, in non-tumor diseases such as IDD, osteoporosis, I/R injury, DOXIC, DR, DN, HSCR, and others, circ-ITCH plays a more complex regulatory role." (PMID 35910224, 2022). "For instance, circ-ITCH expression is downregulated in CRC, where it acts as a tumor suppressor by inhibiting CRC cell proliferation and metastasis." (PMID 34660182, 2021). "The E3 ubiquitin ligase, ITCH, negatively regulates the tumour suppressor protein TP73, providing a therapeutic target to enhance the sensitivity of the tumour cells to the treatment." (PMID 31974512, 2020).